GLIS3 (GLIS family zinc finger 3)
Description:
Acts both as a repressor and an activator of transcription. Binds to the consensus sequence 5'-GACCACCCAC-3' (By similarity).
Synonyms: ZNF515; MGC33662; NDH
Tractability: No criterion of Open Targets' tractability assessment is met for any kind of drug.
Gene: Protein-coding gene on chromosome 9 (3,824,127 to 4,348,392, reverse strand). Ensembl gene ENSG00000107249.
Subcellular location: Nucleus
Subcellular location (Human Protein Atlas): Nucleoplasm; Golgi apparatus; Primary cilium
Gene Ontology:
Molecular function: protein binding; DNA-binding transcription activator activity, RNA polymerase II-specific; DNA-binding transcription factor activity, RNA polymerase II-specific; DNA-binding transcription repressor activity, RNA polymerase II-specific; RNA polymerase II cis-regulatory region sequence-specific DNA binding; RNA polymerase II transcription regulatory region sequence-specific DNA binding; sequence-specific double-stranded DNA binding
Biological process: negative regulation of transcription by RNA polymerase II; positive regulation of transcription by RNA polymerase II; regulation of transcription by RNA polymerase II; transcription by RNA polymerase II
Cellular component: nucleus
Genetic constraint (gnomAD): Loss-of-function variants: 53 observed, 78.09 expected, observed/expected ratio (o/e) 0.68, 90% interval 0.54 to 0.85. The synonymous counts are far from expectation, so gnomAD's model fits this gene poorly and the ratio says little. Missense variants: 1,701 observed, 1,259.9 expected, observed/expected ratio (o/e) 1.35, 90% interval 1.3 to 1.4. Synonymous variants: 684 observed, 520.66 expected, observed/expected ratio (o/e) 1.31, 90% interval 1.23 to 1.4.
Homologues: Orthologues: chimpanzee GLIS3 (98% identical), macaque GLIS3 (96% identical), pig GLIS3 (88% identical), dog GLIS3 (88% identical), guinea pig GLIS3 (88% identical), mouse Glis3 (84% identical), rat Glis3 (84% identical), rabbit GLIS3 (76% identical), tropical clawed frog glis3 (68% identical), zebrafish glis3 (39% identical). Paralogues in human: GLIS1 (31% identical), GLI2 (27% identical), GLI3 (25% identical), GLI1 (21% identical), ZIC2 (15% identical), GLIS2 (15% identical), ZIC5 (14% identical), ZXDC (14% identical), ZIC3 (14% identical), ZIC1 (13% identical), ZXDA (13% identical), ZXDB (13% identical), and 2 more.
Diseases named in the same sentence as GLIS3 in open-access papers:
GLIS3 is named in the same sentence as 117 diseases in open-access papers, as found by Europe PMC text mining. Sharing a sentence is not in itself a finding about the gene and the disease. The quoted sentences say what the papers report.
diabetes (67 papers, 2009 to 2026). "GLIS3 plays a critical role in pancreatic β cells and diabetes, being one of only a few genes implicated in Type 1, Type 2, and Gestational diabetes." (PMID 41542538, 2026). "In this study, we provide greater insights into the causal mechanism of neonatal diabetes and show that during embryonic pancreas development, GLIS3 regulates two distinct stages of the endocrine lineage." (PMID 41542538, 2026). "Syndromic Diabetes: Arises from mutations in pleiotropic transcription factors (GLIS3, GATA6, HNF1B) or metabolic transporters (SLC19A2, WFS1)." (PMID 41614934, 2026). "Sensory Deficits (Vision/Hearing): Often precede or accompany diabetes in WFS1 (Wolfram) or GLIS3 mutations." (PMID 41614934, 2026). "In vitro, GLIS3 deficiency in β-cells activates the intrinsic pathway of apoptosis, thereby increasing susceptibility to diabetes." (PMID 40149950, 2025). "Recently, evidence strongly indicates that mutations in GLIS3 increases type 2 diabetes risk, in addition to GLIS3 involvement in monogenic diabetes." (PMID 40149950, 2025). "Loss-of-function mutations in GLIS3 are implicated in several pathologies, including polycystic kidney disease, diabetes, and hypothyroidism." (PMID 41369402, 2025). "GLIS3 was sequenced in 5471 individuals from the Rare Variants Involved in Diabetes and Obesity (RaDiO) study." (PMID 38051360, 2024). "In contrast, HFD beta cells showed reduced expression of genes associated with beta cell function (i.e., Fos, Fosb, Jun, and the incretin receptor Gipr), and increased expression of stress- and diabetes-associated genes (Fkbp5 and Glis3, respectively)." (PMID 39433757, 2024). "Other genes encode proteins involved in calcium handling (BMP3 and SYNDIG1) or are associated with diabetes mellitus (GLIS3 and TRIB3), suggesting a potential link to accelerated atherosclerosis development." (PMID 38725839, 2024). "Meanwhile, GLIS3 is another recognized gene for diabetes that is associated with the development of beta cells and neonatal diabetes." (PMID 38840168, 2024). "In conclusion, P/LP monoallelic GLIS3 variants contribute to increased type 2 diabetes risk, in addition to GLIS3 involvement in monogenic diabetes." (PMID 38051360, 2024). "GLIS3 has been associated with an increased risk of diabetes, glaucoma, and neurological disorders including Alzheimer’s disease." (PMID 37142620, 2023). "The loci with the largest effect sizes in childhood relative to adults have been associated with an elevated blood glucose level (AADAT) and diabetes (GLIS3)." (PMID 37530217, 2023). "Based on 3D culture, GLIS3−/− human ESCs (hESCs) were induced to act as a high‐throughput platform for drug identification in GLIS3‐associated diabetes." (PMID 37215622, 2023). "GLIS3 has been implicated in previous studies investigating diabetes and hypothyroidism which have been deemed risk factors for OA development." (PMID 38041181, 2023). "Regarding the molecular mechanisms that underlie the associations of GLIS3 and diabetes, little was known until multiple groups independently generated both global and beta-cell-specific GLIS3 knockout models." (PMID 34691077, 2021). "GLIS3’s connection to diabetes has further been reinforced by genome wide association studies (GWAS), which we have previously reviewed." (PMID 34943978, 2021). "Fourthly, another coregulated gene in our fetal and AT tissues, GLIS3, displays mutations responsible for primary CH and diabetes." (PMID 34249923, 2021). "In pancreatic β-cells, the expression of the splicing factor SRSF6 is regulated by GLIS3, a transcription factor encoded by a diabetes susceptibility gene." (PMID 33376132, 2021). "In the pancreatic β-cells, SRSF6 expression is regulated by the diabetes susceptibility gene GLIS3, which encodes an important transcription factor for β-cell development and maintenance of the differentiated phenotype." (PMID 33376132, 2021).
diabetes (continued). "Type 1 diabetes (T1D) and T2D are two genetically distinct diseases, yet GLIS3 is one of the few genes in which common variants have been found to associate with both forms of diabetes." (PMID 31415576, 2019). "Globally Glis3 deficient mice have a decreased beta-cell mass and develop neonatal diabetes in addition to hypothyroidism, and cystic kidney disease." (PMID 31415576, 2019). "In humans common and low frequency GLIS3 variants (MAF > 0.1%) have previously been investigated in relation to diabetes." (PMID 31415576, 2019). "We use this platform to determine the role of GLIS3 in human pancreatic β-cell generation and survival, and to identify a lead hit drug candidate for treating the broad range of human patients who suffer from GLIS3-associated diabetes." (PMID 29992946, 2018). "In mutant mice, neonatal diabetes is associated with decreased insulin levels caused by an impaired β-cell mass, suggesting a relevant role for Glis3 in the regulation of β-cell development and endocrine function." (PMID 30555422, 2018). "As we have learned, some of the diabetes susceptibility genes e.g., GLIS3, PTPN2, BACH2 and Cathepsin H, regulate Bim expression." (PMID 26405162, 2015). "We and others reported defective islet cell differentiation and lethal neonatal diabetes in Glis3-deficient mice." (PMID 23197416, 2013). "In addition to PKD, ubiquitous GLIS3-deficient mice develop neonatal diabetes and hyperglycemia, which are well-established risk factors in the development of renal dysfunction and diabetic nephropathy." (PMID 39505148, 2024). "GLIS3 polymorphism is linked to susceptibility to both T1D and T2D as well as rare mutations also causing neonatal diabetes, demonstrating that expression variation can modify diabetes risk." (PMID 36291702, 2022). "Loss of GLIS3 results in a drastic reduction in insulin expression, leading to hyperglycemia that subsequently induces beta-cell apoptosis and culminates in severe fulminant diabetes.." (PMID 35246208, 2022). "Moreover, we showed that SRSF6, which is regulated by the diabetes candidate gene GLIS3, modulates the splicing of other diabetes susceptibility genes, suggesting the presence of an AS-regulated network with a putative impact on diabetes risk." (PMID 33376132, 2021). "Taken together, these studies highlight the importance of understanding GLIS3’s role in pancreas development, and how it may differ from other genes linked to diabetes." (PMID 34943978, 2021). "Besides Srrm4, the expression of two other neuron-specific splicing factors, Nova1 and Rbfox2, as well as the diabetes gene Glis3, which regulates splicing of Bim3, encoding an apoptosis protein, is lower in NZO than in B6-ob/ob islets." (PMID 34445304, 2021). "In conclusion, we find that rare missense variants in GLIS3 may increase risk of diabetes and elevate levels of plasma glucose." (PMID 31415576, 2019). "β-cell specific inactivation of Glis3 leads to β-cell loss and diabetes." (PMID 29992946, 2018). "While administration of an inhibitor of TGFβ signaling during pregnancy could impose complications, it is possible that it could have potential for GLIS3-associated diabetes in the adults." (PMID 29992946, 2018). "The GLIS3 gene that was detected among smokers is a transcription factor regulating the development of liver, kidney and pancreatic beta cells; it is associated with diabetes and also with liver cancer." (PMID 26959888, 2016). "As in humans, mice defective in Glis3 function develop neonatal diabetes, hypothyroidism, and polycystic kidney disease, while heterozygous Glis3 knockout mice are more susceptible to diet-induced diabetes." (PMID 27270601, 2016). "GLIS3 has been listed as a diabetes susceptibility gene due to its role in the generation of pancreatic beta cells; an alteration in the expression of this gene could repress the generation of beta cells, and may be involved in pancreatic dysfunction." (PMID 25852736, 2015).
diabetes (continued). "GLIS3 deficient mice have a major decrease in beta cell mass and develop neonatal diabetes." (PMID 23737756, 2013). "Genome-wide association studies in large numbers of individuals with type 1 (T1D) or type 2 (T2D) diabetes indicated that common variants near GLIS3 gene are associated with both forms of diabetes, making GLIS3 one of the few candidate genes for both T1D and T2D." (PMID 23737756, 2013). "Moreover, conditional knockout of GLIS3 in adult mice causes defective insulin secretion and increase susceptibility to high fat diet-induced diabetes." (PMID 23737756, 2013). "The fact that recessive loss-of-function mutations in GLIS3 cause severe neonatal diabetes in humans and in transgenic mouse models, secondary to a major decrease in beta cell mass, suggests that this transcription factor is necessary for beta cell development and differentiation." (PMID 23737756, 2013). "The GLIS3 gene region has been identified as a susceptibility risk locus for both type 1 and type 2 diabetes—it is actually the only locus showing association with both forms of diabetes and the regulation of blood glucose." (PMID 23737756, 2013). "Similarly, GLIS3 was identified as a susceptibility risk locus for both T1D and T2D in GWAS and decreased expression of GLIS3 may contribute to both forms of diabetes by favoring β-cell apoptosis." (PMID 37841955, 2023). "GLIS3 might control insulin gene transcription and played a role in insulin secretion in β cells, while deficiency of GLIS3 induced apoptosis of the β cells of pancreatic islets and caused diabetes." (PMID 38087213, 2023). "Thus, GLIS3 appear to be implicated in various diabetes forms." (PMID 31415576, 2019). "In a Japanese study, a GLIS3 variant (p.A908V) protecting against T1D was found among approximately 3,000 Japanese patients with T1D and control individuals, indicating that variants in GLIS3 may not only have a deleterious effects on diabetes." (PMID 31415576, 2019). "In addition, the association of GLIS3 CNVs with diabetes was reported." (PMID 23349908, 2013). "Thus, even a partial decrease in GLIS3 expression, as may be the case in some of the diabetes-predisposing gene polymorphisms, enhances beta cell sensitivity to basal, immune- or metabolic stress-induced apoptosis." (PMID 23737756, 2013). "Within pancreatic β cells, GLIS3 functions as an activator and repressor of gene expression and regulates several critical β cell and diabetes related genes, including the insulin gene, Ins21,2,9,10." (PMID 41542538, 2026). "Because these factors—including GLIS3, PAX6, GATA6, HNF1B, and NEUROG3—are pleiotropic regulators active in multiple organ systems, their deficiency rarely causes isolated diabetes." (PMID 41614934, 2026). "As GLIS3 plays a critical role in pancreatic beta cells and diabetes, we examined this possibility in pancreatic islets from wild-type mice and mice with a genetic disruption of the leptin receptor (db/db), which leads to a diabetic phenotype." (PMID 41369402, 2025). "Great insights have been obtained about the biological functions of GLIS3 and its regulatory role in various pathologies, including diabetes, hypothyroidism, polycystic kidney disease, and cancer." (PMID 41369402, 2025). "GLIS3, a maternally imprinted gene, is a candidate gene for diabetes, and we have previously shown that palmitate exposure altered the expression and DNA methylation of GLIS3 in human pancreatic islets." (PMID 39707713, 2025). "Among these interactors, EIF2AK3, GLIS3, IER3IP1, and PLAGL1 are linked to Diabetes mellitus in Swiss-Prot." (PMID 34715892, 2021). "Another important candidate is the diabetes gene Glis3, a transcription factor which regulates splicing of the pro-apoptotic BH3 protein Bim." (PMID 34445304, 2021). "A significant body of research now exists tying GLIS3 to the regulation of pancreatic β-cells and diabetes." (PMID 34943978, 2021).
diabetes (continued). "Previous reviews have sought to summarize GLIS3’s role in diabetes, congenital hypothyroidism, as well as a variety of other diseases." (PMID 34943978, 2021). "One such transcription factor that has been increasingly tied to both β-cell development and the development of diabetes in humans is GLIS3." (PMID 34943978, 2021). "Taking into account that SRSF6 was initially found as a downstream target of the diabetes candidate gene GLIS3 in the rat cell line Ins1E, we tested for this association in human cells." (PMID 33376132, 2021). "Additional studies have since reinforced this linkage, firmly connecting GLIS3 to diabetes, hypothyroidism, polycystic kidney disease, as well as a host of additional phenotypes." (PMID 34943978, 2021). "Our findings provide new areas for further investigation into the roles of GLIS3 in the pathophysiology of diabetes mellitus." (PMID 34093443, 2021). "As a significant progress has been made in understanding some of GLIS3’s roles in pancreas development and diabetes, we sought to compare current knowledge on GLIS3 within the pancreas to that of other islet enriched transcription factors." (PMID 34943978, 2021). "Similar to GLIS3, the PLAGL1 gene encodes for a zinc finger protein associated with diabetes and has been nominated as a tumor suppressor." (PMID 34715892, 2021). "Interestingly, here we find decreased expression in parallel with increased DNA methylation of several candidate genes for T2D, such as TCF7L2 and GLIS3, in palmitate-treated human islets, suggesting that lipid-induced epigenetic modifications may affect the risk for diabetes." (PMID 24953961, 2014). "We challenged Glis3+/− mice with high fat diet for 20 weeks and found that they developed diabetes because of impaired beta cell mass expansion." (PMID 23197416, 2013). "We conclude that normal Glis3 expression is required for pancreatic beta cell function and mass maintenance during adulthood, which impairment leads to diabetes in adults." (PMID 23197416, 2013). "We showed that tamoxifen (TAM)-induced deletion of Glis3 in adult animals leads to acute downregulation of insulin production, hyperglycaemia and subsequently beta cells apoptosis and fulminant diabetes." (PMID 23197416, 2013). "Treatment of these mice with TAM produces beta cell-specific inactivation of Glis3 in adult animals, which led to fulminant diabetes." (PMID 23197416, 2013). "Intriguingly, we found that haploinsufficiency of Glis3 made the adult Glis3+/− mice much more prone than wild-type to develop high fat diet (HFD)-induced diabetes due to an impairment of beta cell proliferation and beta cell mass expansion in response to HFD." (PMID 23197416, 2013). "Novel variants in the genes ARAP1, GLIS3, MADD, NOTCH2 and WFS1 need further investigation to reveal their possible role in diabetes." (PMID 22662265, 2012). "This raised the possibility that changes in GLIS3 isoform expression may have a role in the pathophysiology of diabetes." (PMID 41369402, 2025). "The Glis3-Manf pathway appears to be an important fulcrum for diabetes development." (PMID 36291702, 2022). "Additional studies using primary human islets might establish a more physiologically relevant assessment of GLIS3 function and provide greater insights into the potential of GLIS3 as a therapeutic target in the management of diabetes." (PMID 34943978, 2021). "Also a known MODY (Maturity Onset Diabetes of the Young) gene, GLIS3 is expressed predominantly in the pancreas, thyroid, and kidney." (PMID 34691077, 2021). "Based on the association of common GLIS3 variants with various forms of diabetes and the biological role of GLIS3 in beta-cells, we sequenced GLIS3 in non-diabetic and diabetic Danes to investigate the effect of rare missense variants on glucose metabolism." (PMID 31415576, 2019).